WEE1 (WEE1 G2 checkpoint kinase)
Diseases named in the same sentence as WEE1 in open-access papers (continued):
Sharing a sentence is not in itself a finding about the gene and the disease.
endometrial cancer (continued). "In conclusion, our preclinical findings indicate that Wee1 inhibition can enhance the response to EphA2-targeted therapeutics in endometrial cancer; this strategy thus warrants further development." (PMID 36835335, 2023). "Under this perspective, WEE1 inhibition has been investigated in several neoplasms in phase I trials showing efficacy in ovarian and endometrial carcinomas." (PMID 35052761, 2021). "The cytotoxic potential of WEE1 inhibitors on endometrial cancer cells was assessed by CCK8 assay." (PMID 38169513, 2024). "The results indicated that WEE1 inhibitors hindered the migration of endometrial cancer cells." (PMID 38169513, 2024). "Thus, WEE1 inhibitors are anticipated to offer a promising novel avenue to extend survival times for patients suffering from endometrial cancer." (PMID 38169513, 2024). "However, our study did not thoroughly investigate the signaling pathway through which WEE1 inhibitors exert their antitumor effects in endometrial cancer or explore potential combination therapy strategies." (PMID 38169513, 2024). "The results suggested WEE1 was expressed in all tumor tissues of endometrial cancer patients." (PMID 38169513, 2024). "To test our hypothesis that Wee1 inhibition sensitizes cells to EphA2-targeted therapy, we examined the anti-tumor effects of both agents in endometrial cancer mouse models and evaluated potential mechanisms of synergy." (PMID 36835335, 2023). "As reviewed above, the Wee1 inhibitor adavosertib is able to ameliorate patients’ survival benefits and has the potential to be a good candidate for the treatment of advanced or recurrent/metastatic endometrial cancer." (PMID 37109350, 2023). "Therefore, CCNE1 amplification is a biomarker for the application of WEE1 inhibitors in endometrial cancer." (PMID 37109350, 2023). "However, studies on WEE1 inhibitors in endometrial cancer remain in nascent stages." (PMID 38169513, 2024). "In vitro and in vivo studies have reported sensitivity of UCS cell lines to the ATR inhibitor elimusertib, and a separate study has reported synergy between Wee1 and ATR inhibition in CCNE1-amplified ovarian and endometrial cancer models." (PMID 40678577, 2025). "In the present study, we identified the Wee1 kinase inhibitor, MK1775, as a synergistic partner to EphA2-targeted therapy in endometrial cancer cells." (PMID 36835335, 2023). "Given that tumors in recurrent endometrial cancer patients tend to display greater malignancy and likely require increased WEE1 for DNA repair, we investigated WEE1 expression in tumor tissues from recurrent and non-recurrent endometrial cancer patients." (PMID 38169513, 2024). "Compared with non-recurrent patients, WEE1 protein is significantly overexpressed in the cancerous tissues from patients with recurrent endometrial cancer." (PMID 38169513, 2024). "Given that the prognostic significance of Wee1 has not been reported in endometrial cancer, relevant studies need to be conducted in the near future." (PMID 37109350, 2023).
gastrointestinal stromal tumor (10 papers, 2008 to 2025). "Targeting the WEE1 kinase was reported to strengthen the antitumor activity of imatinib via promoting KIT autophagic degradation in gastrointestinal stromal tumors." (PMID 33516270, 2021). "High expression of Wee1 is positively corelated with cell proliferation and malignancy; and Wee1 inhibition could suppress gastrointestinal stromal tumor cell proliferation, and induce apoptosis and cell cycle arrest." (PMID 36699046, 2022).
head and neck squamous cell carcinoma (9 papers, 2019 to 2025). A squamous cell carcinoma that arises from any of the following anatomic sites: lip and oral cavity, nasal cavity, paranasal sinuses, pharynx, larynx, and salivary glands. "Finally, we note that alterations in MMB–FOXM1-driven transcription are seen in multiple cancers, including human papillomavirus-positive head and neck squamous cell carcinoma, where it causes sensitivity to WEE1 inhibition." (PMID 35444283, 2022). "Both IAP and WEE1 inhibitors have demonstrated therapeutic efficacy in in vitro pre-clinical models of head and neck squamous cell carcinoma (HNSCC)." (PMID 36831373, 2023). "Another example of such an approach is the combined inhibition of CHK1 and WEE1 that was found to be cytotoxic for head and neck squamous cell carcinoma cell lines." (PMID 38137049, 2023). "Here, we have analysed the response of head and neck squamous cell carcinoma (HNSCC) cell lines, spheroids and patient-derived organoids to X-rays and proton beam therapy (PBT) in the presence of either a Chk1 (MK-8776) or a Wee1 (MK-1775) inhibitor." (PMID 39994186, 2025). "Besides, WEE1 inhibition effectively reversed resistance to BRAF inhibitors and AURKA inhibitor (MLN8237) in HPV- HNSCC (head and neck squamous cell carcinoma." (PMID 38231277, 2024).
lung adenocarcinoma (9 papers, 2015 to 2025). A carcinoma that arises from the lung and is characterized by the presence of malignant glandular epithelial cells. "Lung adenocarcinoma (LUAD) demonstrated a contrasting pattern, where elevated HuR linked to reduced WEE1 inhibitor (MK-1775) efficacy (R = -0.28, p < 0.01) but enhanced sensitivity to platinum agents (Cisplatin) and wild-type EGFR-TKIs (Erlotinib; R = 0.35-0.42, p < 0.01)." (PMID 40853971, 2025). "Furthermore, we investigated the effects of a combination of sotorasib with the cytotoxic chemotherapy pemetrexed, one of the standard treatments for lung adenocarcinoma, and confirmed that pemetrexed did not enhance the efficacy of sotorasib, unlike the combination of sotorasib and WEE1 inhibitors." (PMID 38776912, 2024).
pancreatic ductal adenocarcinoma (9 papers, 2015 to 2025). An infiltrating adenocarcinoma that arises from the epithelial cells of the pancreas. "This study evaluated the combinational effect of a DNA-damaging agent and a WEE1 inhibitor (AZD 1775) in patient-derived organoids (PDOs) generated from pancreatic ductal adenocarcinoma (PDAC) cells." (PMID 40585160, 2025). "ATM and WEE1 (DNA damage cell-cycle checkpoint protein) inhibition has been shown to decrease CXCR2 expression and surface PDL1 exposure in human pancreatic ductal adenocarcinoma (PDAC) cells with KRAS mutations." (PMID 38473997, 2024). "In KRAS-mutant pancreatic ductal adenocarcinoma, concurrent inhibition of WEE1 and ERK demonstrated enhanced tumor growth suppression and apoptosis compared to WEE1 inhibition alone." (PMID 40885709, 2025). "In previous studies, we demonstrated that ATR/Chk1 inhibitors selectively enhanced F10 but not 5-FU cytotoxicity in human CRC cell lines, while inhibitors of the ATR/Chk1/Wee1 pathway enhanced CF10 but not 5-FU cytotoxicity in pancreatic ductal adenocarcinoma." (PMID 38611037, 2024).
small cell lung carcinoma (9 papers, 2018 to 2024). Small cell lung cancer (SCLC) is a highly aggressive malignant neoplasm, accounting for 10-15% of lung cancer cases, characterized byrapid growth, and early metastasis. "Small cell lung cancer patient-derived circulating tumour cell explant models with HRR-deficiency were found to respond well to olaparib in combination with WEE1 inhibitor AZD1775." (PMID 32526907, 2020). "In small-cell lung cancer, Axl promotes primary and acquired resistance to WEE1 (WEE1 G2 checkpoint kinase) inhibition." (PMID 32370748, 2020). "Indeed, AZD1775-resistant small cell lung cancer models were shown to have elevated expression of AXL, pS6, and MET genes that a WEE1/AXL or WEE1/mTOR inhibitor combination could overcome the resistance in vitro and in vivo." (PMID 30068368, 2018).
brain tumors (8 papers, 2014 to 2026). "Although studies on WEE1 inhibition in meningiomas are limited, preclinical evidence from other brain tumors suggest that WEE1 inhibitors can enhance the effects of radiation and induce tumor cell death." (PMID 39935847, 2024). "Here, we discuss preclinical progress in molecular targeting of ATM, ATR, CHK1, CHK2, and WEE1, checkpoint kinases in the treatment of brain tumors, and review current clinical phase I-II trials." (PMID 35158967, 2022). "In the following, the current knowledge of the effect of inhibition of ATM, ATR, CHK1, CHK2, and WEE1 kinases regarding the radiation treatment of brain tumors will be presented." (PMID 35158967, 2022). "A search of the NIH ClinicalTrials.gov database for clinical trials on cell cycle checkpoint inhibitors in brain tumors identified two trials on inhibitors of ATM and CHK1, respectively, and five on the WEE1 inhibitor AZD1775." (PMID 35158967, 2022). "In this review, we summarize the knowledge in the field of brain tumor treatment with radiation therapy and cell cycle checkpoint inhibition via targeting ATM, ATR, CHK1, CHK2, and WEE1 kinases." (PMID 35158967, 2022). "Cell cycle checkpoint inhibition is still in its infancy but while ATM, CHK1, and WEE1 inhibitors resulted in successful sensitization of various tumor types, including primary brain tumors, ATM and CHK2 inhibitors are less studied in brain tumors." (PMID 35158967, 2022). "In brain tumors, the expression of Wee1 kinase was upregulated only in tumor cells, not in normal cerebellum, and the upregulated kinase had an important role in cancer cell survival." (PMID 24960176, 2014).
breast tumor (8 papers, 2009 to 2025). "To determine whether WEE1 gene expression was associated with survival, we analyzed publicly available gene expression datasets for ER+ breast tumors." (PMID 34277427, 2021). "Together, findings from our study supports the potential clinical use of anti-WEE1 therapy for ER+ breast tumors that have acquired resistance to endocrine therapy and are intrinsically resistant to CDK4/6 inhibitors." (PMID 34277427, 2021). "Our results indicate, for the first time, that TTP inhibits c-Jun transcription by blocking NF-κB p65 nuclear translocation that results in Wee1 induction and cell cycle arrest at the S phase, leading to suppression of breast tumor cell proliferation." (PMID 26497679, 2015). "We then examined a well-annotated series of breast tumours and found that 35% exhibited levels of WEE1 expression similar to those of CAL51 cells, which are sensitive to WEE1 inhibition." (PMID 19357772, 2009). "We overexpressed c-Jun in breast tumor cells and then measured Wee1 expression." (PMID 26497679, 2015). "Moreover, reconstitution of c-Jun in TTP-expressing breast tumor cells diminishes Wee1 overexpression and promotes cell proliferation." (PMID 26497679, 2015). "Indeed, c-Jun significantly reduces Wee1 expression, indicating a direct correlation between c-Jun and Wee1 in breast tumor cells." (PMID 26497679, 2015). "Therefore, we interrogated the expression of WEE1 in publicly available datasets that detail the expression profiles of human breast tumour cell lines and tumours." (PMID 19357772, 2009). "In addition, DDX5 and ZC3H12D were also positively and negatively correlated with the expression of several cell cycle‐promoting genes, such as WEE1 and CDK2, in human breast tumor tissues." (PMID 41263459, 2025). "Relapse-free survival over time (rfs_t) was estimated by Kaplan-Meier plots from two databases (GSE2034, GSE7390) showed that high WEE1 gene expression significantly correlated with unfavorable prognosis in lymph node negative ER+ breast tumors." (PMID 34277427, 2021). "Since TTP inhibits c-Jun and increases Weel expression in breast tumor cells, we tested whether TTP increases Wee1 expression through inhibiting c-Jun." (PMID 26497679, 2015).
medulloblastoma (8 papers, 2012 to 2026). A malignant, invasive embryonal neoplasm arising from the cerebellum. "An example of this is WEE1, a tyrosine kinase involved in the G2/M checkpoint and overexpressed in pHGGs and high risk medulloblastoma." (PMID 34277419, 2021). "Molecular analyses of primary medulloblastoma have also demonstrated WEE1 overexpression alongside amplification of the MYC family of protooncogenes (MYC or MYCN), which characterize high risk disease in patients from SHH, Group 3, and Group 4 sub-groups." (PMID 34277419, 2021). "Taken together, these findings highlight mitotic kinases and, in particular, WEE1 as a rational therapeutic target for medulloblastoma." (PMID 24661910, 2014). "Our data show that the small molecule inhibitor of WEE1, MK-1775, is a potent inhibitor of medulloblastoma cell growth and synergizes with cisplatin to decrease cell proliferation in vitro." (PMID 24661910, 2014). "In summary our data supports a role for WEE1 in regulating the G2-M checkpoint in medulloblastoma and validated WEE1 as a therapeutic target." (PMID 24661910, 2014). "We then chose to determine the ability of medulloblastoma cells to undergo an unlimited number of divisions following inhibition of WEE1 by performing a colony forming assay." (PMID 24661910, 2014). "We next evaluated WEE1 protein in two normal pediatric cerebellum samples, one adult normal cerebellum sample and in a panel of well characterized medulloblastoma cell lines." (PMID 24661910, 2014). "We show that genetic and chemical inhibition of one of these kinases, WEE1, potently suppresses cell growth, induces apoptosis and decreases tumor volume in vivo in medulloblastoma." (PMID 24661910, 2014). "A combination of in vitro and in vivo studies clearly indicates that WEE1 mediates medulloblastoma tumorigencity and represents a novel therapeutic target." (PMID 24661910, 2014). "Comparison of normal cerebellum with medulloblastoma showed significant over expression of WEE1 (p < 9.35E-7) in this disease." (PMID 24661910, 2014). "This study shows that WEE1 is over expressed and functionally important in medulloblastoma." (PMID 24661910, 2014). "We first examined the expression of WEE1 in an independent cohort of 90 medulloblastoma samples." (PMID 24661910, 2014). "We have demonstrated that WEE1 inhibition sensitizes medulloblastoma cells to cisplatin in vitro." (PMID 24661910, 2014). "Detailed animal modeling of medulloblastoma with assessment of potential biomarkers as well as pharmacokinetics will provide further data in evaluating the effectiveness of WEE1 inhibition in conjunction with cisplatin in eradicating medulloblastoma cells in vivo and prolonging patient survival." (PMID 24661910, 2014). "A series of pyrazolopyrimidinone analogs were synthetized and, in 2016, Matheson and collaborators reported a compound (CJM-061) that showed the same Wee1 inhibitory efficacy of AZD1775, but had reduced single-agent cytotoxicity in medulloblastoma cells." (PMID 34639030, 2021). "WEE1 protein is not present in pediatric (UPN 514, 605) or adult cerebellum but was present in varying amounts in the 6 medulloblastoma cell lines evaluated." (PMID 24661910, 2014).
metabolic syndrome (8 papers, 2013 to 2024). A cluster of metabolic risk factors for CARDIOVASCULAR DISEASES and TYPE 2 DIABETES MELLITUS. "A notable proportion of genes within the enriched pathways in liver are related to the biological clock, including Wee1, Per2 and Slc5a6, each previously reported to be associated with the development of metabolic syndrome." (PMID 30619467, 2018).
thyroid cancer (8 papers, 2014 to 2025). "Adavosertib sensitivity was associated with lower Wee1 protein levels in thyroid cancer cell lines." (PMID 34298699, 2021). "Excess iodine may increase the expression of cell cycle–related proteins, such as Wee1 and cyclin-dependent kinase 1 in thyroid cancer cells promoting proliferation." (PMID 41228194, 2025). "Our data suggest that thyroid cancer cell lines with lower Wee1 expression rely on Wee1 activity, and interrupting Wee1 with adavosertib impairs cell growth more significantly than thyroid cancer cells with higher Wee1 expression." (PMID 34298699, 2021). "Taken together, these findings suggested that high iodine induced the proliferation of thyroid cancer cells through AKT-mediated Wee1/CDK1 axis, which provided new insights into the regulation of proliferation of thyroid cancer cells by iodine." (PMID 33796458, 2021). "Further studies uncovered that high iodine exerted its roles by activating AKT/Wee1/CDK1 axis and accelerating cell cycle progression in thyroid cancer." (PMID 33796458, 2021). "Therefore, we inferred that AKT/Wee1/CDK1 axis might be activated under exposure to high iodine, thereby promoting the proliferation of developed thyroid cancer cells." (PMID 33796458, 2021). "This study was designed to explore whether AKT-mediated Wee1/CDK1 axis is involved in the proliferation of PTC and ATC cells induced by high iodine, with a new insights that iodine plays the role on cell proliferation in thyroid cancer." (PMID 33796458, 2021).